NATD1 (N-acetyltransferase domain containing 1)
Synonyms: C17orf103; GTLF3B; MGC33894
Tractability: PROTAC: ubiquitination databases record sites on it; its protein half-life has been measured.
Gene: Protein-coding gene on chromosome 17 (21,238,870 to 21,253,410, reverse strand). Ensembl gene ENSG00000274180.
Gene Ontology:
Molecular function: protein binding
Genetic constraint (gnomAD): Loss-of-function variants: 6 observed, 10.14 expected, observed/expected ratio (o/e) 0.59, 90% interval 0.32 to 1.17. The upper end of that interval is the gene's LOEUF score, 1.17, which puts it in group 5 of 6, group 1 being the genes least tolerant of losing a copy. Missense variants: 131 observed, 131.66 expected, observed/expected ratio (o/e) 0.99, 90% interval 0.86 to 1.15. Synonymous variants: 65 observed, 58.98 expected, observed/expected ratio (o/e) 1.1, 90% interval 0.9 to 1.36.
Homologues: Orthologues: chimpanzee NATD1 (100% identical), dog NATD1 (100% identical), guinea pig NATD1 (100% identical), macaque NATD1 (99% identical), pig NATD1 (96% identical), mouse Natd1 (90% identical), rat Natd1 (90% identical), zebrafish natd1 (72% identical), zebrafish im:6904045 (42% identical), Drosophila melanogaster CG32163 (27% identical), Caenorhabditis elegans ZK1098.11 (27% identical).
Diseases named in the same sentence as NATD1 in open-access papers:
NATD1 is named in the same sentence as 1 disease in open-access papers, as found by Europe PMC text mining. Sharing a sentence is not in itself a finding about the gene and the disease.
NATD1 shares sentences with these, for which no sentence is quoted: Arthritis (1 paper).